SMYD3 (SET and MYND domain containing 3)
Diseases named in the same sentence as SMYD3 in open-access papers (continued):
Sharing a sentence is not in itself a finding about the gene and the disease.
breast carcinoma (continued). "SMYD3 suppresses the methylation of H2A.Z1, thereby inhibiting Anp32e-mediated dissociation of H2A.Z1 from chromatin, increasing cyclin A1 expression, and encouraging breast cancer progression." (PMID 39199381, 2024). "More importantly, SMYD3 could potentiate Akt signaling pathway in GC, pancreatic ductal adenocarcinoma, lung adenocarcinoma, breast cancer, colon cancer, and bladder cancer." (PMID 37386026, 2023). "Furthermore, in breast cancer, SMYD3 drives cell cycle progression by upregulating the transcription of cyclin A1 whereas, in hepatocellular carcinoma, SMYD3 promotes proliferation through stimulating CDK2 transcription." (PMID 35406445, 2022). "Likewise, a separate study indicated that a SYMD3 inhibitor, inhibitor-4, demonstrated potent impacts on two breast cancer lines, MCF7 and MDA-MB-231 (both lines linked to overexpression of SMYD3)." (PMID 34842655, 2021). "After initial hit identification in vitro, we purchased and tested five novel small molecule SMYD3 inhibitors and discovered that Inhibitor-4 significantly reduces breast cancer proliferation, arrests the cell cycle, and induces apoptosis without impacting wild type cells." (PMID 33333978, 2020). "Notably, treatment with the SMYD3 inhibitor BCI-121 reduces the invasive ability of mesenchymal breast cancer cell in vivo, in a zebrafish xenograft model." (PMID 31935919, 2020). "Additionally, immunocytochemistry data have shown elevated levels of SMYD3 expression in breast cancer cell lines comparing to normal cell line." (PMID 33333978, 2020). "High SMYD3 expression was critical for the development of breast cancer cells." (PMID 29089464, 2018). "EZH2 rs12670401 and rs6464926 polymorphisms, EZH2 and SMYD3 expression, clinical staging, lymph node metastasis, human epidermal growth factor receptor-2 (HER2) status, and metastasis may be correlated with breast cancer susceptibility and prognosis." (PMID 29089464, 2018). "The increase in E2F in copy number of the region could enhance the affinity of SMYD3 and E2F-1 and increase the possibility in occurrence of breast cancer and poor prognosis." (PMID 29089464, 2018). "The results suggested that EZH2 and SMYD3 were in high expression in breast cancer cells." (PMID 29089464, 2018). "There was a distinctive difference in allele frequency (χ2 =9.1, P=0.034) and genotype frequency (χ2 =39.971, P<0.001) of SMYD3 VNTR, and 3 allele could increase the susceptibility to breast cancer (OR =1.305, 95% CI: 1.097–1.552, P=0.003)." (PMID 29089464, 2018). "The results suggested that EZH2 and SMYD3 were in high expression in breast cancer tissues." (PMID 29089464, 2018). "Besides, our results revealed that EZH2 and SMYD3 were in high expression in breast cancer tissues and cells." (PMID 29089464, 2018). "SMYD3 is overexpressed in several malignancies including esophageal squamous cell carcinoma, gastric cancer, hepatocellular carcinoma, prostate cancer, leukemia and breast cancers." (PMID 28933369, 2017). "However, amp/gain or high expression level of SMYD3 was negatively correlated with shorter survival in breast cancer patients." (PMID 25537518, 2015). "Notably, we found that eight HMTs exhibited high-level amplification in more than 5% of breast cancers, and five of these eight HMTs (SMYD3, SETDB1, ASH1L, WHSC1L1, and SMYD2) had high-level amplification in more than 10% of samples." (PMID 25537518, 2015). "Endogenous expression of SMYD3 is undetectable or very weak in most normal human tissues whereas significant up-regulation was observed in the great majority of investigated colorectal carcinoma, hepatocellular carcinoma, and breast cancer specimens." (PMID 23285160, 2012). "The findings that Smyd3 is substantially upregulated in most CRCs, HCCs, and breast cancer tissues support a paradigm in which aberrant expression of chromatin-modifying enzymes, leading to a disturbance in established epigenetic patterns, can ultimately result in tumorigenesis." (PMID 24710145, 2011).
breast carcinoma (continued). "Smyd3-Shcbp1 expression could be reversed by trametinib treatment, and the combinatory treatment of trametinib with αPD1 enhances the function of effector T cells and sensitizes mammary tumors with elevated SMYD3 and SHCBP1 to αPD1 treatment." (PMID 40157910, 2025). "The methyltransferase SET and MYND domain-containing protein 3 (SMYD3) enables H2A.Z1 methylation, thereby reducing the removal of H2A.Z1 from chromatin by Anp32e, increasing cell cycle-related protein expression, and promoting breast cancer cell proliferation." (PMID 39199381, 2024). "In addition, blocking SMYD3 with BCI121 inhibited ZNF8‐mediated lung metastasis in breast cancer." (PMID 39225541, 2024). "Our results confirmed that targeting SMYD3 can inhibit ZNF8‐mediated invasion and metastasis of breast cancer cells, indicating that targeting the mechanism by which ZNF8 recruits SMYD3 may be an effective strategy for the TGF‐β‐mediated lung metastasis of breast cancer." (PMID 39225541, 2024). "Furthermore, SMYD3 knockdown resulted in decreased cellular proliferation of breast cancer cells." (PMID 33637115, 2021). "Finally, the novel SMYD3 inhibitor presented here caused apoptosis in breast cancer cell lines without affecting the normal breast cell line." (PMID 33333978, 2020). "H2A.Z.1 methylation by SET and MYND domain containing 3 (SMYD3) indeed prevents the removal of this histone variant from chromatin by ANP32E and stimulates the expression of growth-associated genes including cyclin A1, thus promoting breast cancer cell proliferation." (PMID 33167489, 2020). "However, the correlation of EZH2 and SMYD3 polymorphisms with breast cancer susceptibility and prognosis has not yet been reported." (PMID 29089464, 2018). "To examine whether SMYD3‐mediated methylation influences the phosphorylation status of HER2 protein, we knocked down SMYD3 in breast cancer cell lines using specific siRNAs and compared autophosphorylation levels of HER2 at Tyr 1248 that was indicated to be essential for HER2 activity." (PMID 28639750, 2017). "Altogether, these data provide a strong correlation between elevated levels of SMYD3 in PABC, BRCA1, and invasive lobular breast cancers, making it a very important therapeutic target to interrogate in breast cancer." (PMID 40157910, 2025). "SMYD3 inhibition with the novel compound EM127 showed a synergistic effect with CHTs in colorectal, gastric, and breast cancer cells, tumorspheres, and preclinical colorectal cancer models." (PMID 38812026, 2024). "Overall, our data revealed that SMYD3 can act as a bridge between the AMPK and mTOR pathways upon neocarzinostatin-induced DNA damage in gastrointestinal and breast cancer cells." (PMID 37998381, 2023). "Mechanistically, SMYD3 has been shown to interact and activate the HER2 receptor, estrogen receptor, VEGFR1, and SMAD3 in breast cancer cells, and it promotes cell proliferation and colony formation." (PMID 33637115, 2021). "We used two breast cancer cell lines (MCF7 and MDA-MB-231) that were previously shown to overexpress SMYD3 compared with the wild type breast epithelial cell line MCF10A." (PMID 33333978, 2020). "The impact of SMYD3 inhibitors on growth of breast cancer cells was tested by adding 50, 100 and 200 μM of Inhibitor-4 or BCI-121 to breast cancer cell lines (MCF7 and MDA-MB-231) and normal breast epithelial cell line (MCF10A)." (PMID 33333978, 2020). "SMYD3-mediated H2AFZ methylation accelerates G1-S transition and promotes breast cancer proliferation." (PMID 31777591, 2019). "The mRNA and protein expression of EZH2 and SMYD3 in normal breast epithelial cells MCF-10A and breast cancer cells MCF-7, MDA-MB-231, T47D, and Bcap-37 were detected by RT-qPCR and Western blotting." (PMID 29089464, 2018). "We also found that SMYD3 and WHSC1L1 were prevalently overexpressed in several Luminal breast cancer cell lines." (PMID 25537518, 2015).
breast carcinoma (continued). "Among the five most frequently amplified HMT genes (frequency>10%) in breast cancers, four were localized on the long arm of chromosome 1, with SETDB1 at 1q21.3, ASH1L at 1q22, SMYD2 at 1q32.3, and SMYD3 at 1q44." (PMID 25537518, 2015). "Next, we performed quantitative RT-PCR (qRT-PCR) analysis to measure the mRNA expression level of eight HMTs (SETDB1, ASH1L, SMYD2, SMYD3, SETD1A, WHSC1L1, SUV420H1, and SETDB2) in 20 breast cancer cell lines." (PMID 25537518, 2015). "Notably, in the case of breast carcinoma, the frequency of high-level amplification accounted for 18.6% and 19.2% of the alterations in SMYD2 and SMYD3, respectively." (PMID 38892284, 2024). "The ability of SMYD3 to increase the expression of the oncogene WNT10B and promote the epithelial–mesenchymal transition (EMT) process is thought to contribute to metastatic breast cancer." (PMID 34201935, 2021). "In our previous testing of Inhibitor-4, we demonstrated its ability to reduce the proliferation and viability of SMYD3-positive breast cancer cells without impacting wild-type breast epithelial cells." (PMID 35076487, 2021). "Nevertheless, TGFβ treatment did not induce a significant increase in SMYD3 transcript levels in breast cancer epithelial cells, suggesting that SMAD3-dependent regulation is context specific." (PMID 31935919, 2020). "We also demonstrated that Inhibitor-4 arrests the cell cycle in breast cancer cells without affecting normal cells, which demonstrates an improvement over BCl-121, a previously-developed SMYD3 inhibitor." (PMID 33333978, 2020). "Unfortunately, we failed to reveal any correlations between SMYD3 VNTR polymorphism and breast cancer susceptibility and prognosis." (PMID 29089464, 2018). "Result of Cox multivariate analysis showed that EZH2 rs12670401, EZH2 rs6464926 and clinical staging, mRNA and protein expression of EZH2 and SMYD3, lymph node metastasis, HER2 status, and metastasis situation were independent prognostic factors for survival rate of breast cancer patients." (PMID 29089464, 2018). "Similarly, inhibition of SMYD3 expression by Novobiocin inhibits the proliferation and migration of MDA-MB-231 breast cancer cells in a dose-dependent manner." (PMID 28933369, 2017). "SET and MYND domain-containing protein 3 (SMYD3) is a H3K4-specific dimethyltransferase and trimethyltransferase that plays an important role in oncogenesis, as noted by its upregulation in colorectal carcinoma, hepatocellular carcinoma, and breast cancer." (PMID 27242892, 2016). "SMYD3 is overexpressed in most hepatocellular (HCC) and colorectal carcinomas (CRC) and its upregulation has been proven to be critical in the proliferation of breast cancer cells." (PMID 24710145, 2011). "The amplification provides further support for the role in general oncogenic process of SMYD3, which may be independent of BRCA1 mutations, as such mutations are only identified in a small fraction (2–4%) of human breast cancers." (PMID 40157910, 2025). "Because Smyd3 is highly expressed in many types of cancers and plays critical roles in cell cycle alteration, apoptosis, and EMT, increased ERα-SMYD3 signaling before, during, and post pregnancy could significantly contribute to PABC and breast cancer formation in general." (PMID 40157910, 2025). "Moreover, SMYD3 expression was significantly negatively correlated with poor breast cancer prognosis in patients with high ZNF8 expression but not in patients with low ZNF8 expression." (PMID 39225541, 2024). "Moreover, our results revealed that SMYD3 could upregulate the expression of target genes and the invasion and metastasis ability of breast cancer cells, while TGF‐β inhibitor SB431542 could significantly inhibit these promoting effects of SMYD3." (PMID 39225541, 2024).
breast carcinoma (continued). "To further elucidate SMYD3 function in the crosstalk between its binding partners AMPK and mTOR upon NCS exposure, we treated HCT-116 and AGS gastrointestinal cancer cells and the MDA-MB-231 breast cancer cell line with the novel active site-selective covalent SMYD3 inhibitor EM127." (PMID 37998381, 2023). "SET and MYND domain-containing protein 3 (SMYD3), a member of the SET and MYND domain family of lysine methyltransferases, is overexpressed in various types of human cancers, including prostate cancer, breast cancer, colon cancer, colorectal cancer, ovarian cancer, and HCC." (PMID 34301921, 2021). "Interestingly, up-regulation of SMYD3 was found in various kinds of tumors, including HCC, lung adenocarcinoma, breast cancer, and pancreatic ductal adenocarcinomas, which indicating SMYD3 might play an important role in the development of human cancer." (PMID 29029425, 2017).
hepatocellular carcinoma (41 papers, 2006 to 2025). A malignant tumor that arises from hepatocytes. "Loss- and gain-of-function studies have shown that SMYD3 contributes to the migration, invasion, metastasis, and stemness of sorafenib-resistant hepatocellular carcinoma cells." (PMID 39482529, 2024). "Several studies have revealed that lung, breast, pancreatic, colorectal, and hepatocellular carcinoma are highly associated with SMYD3 overexpression." (PMID 33333978, 2020). "Since the initial finding, linking Smyd3 to hepatomas and colorectal carcinomas, a polymorphism involving a transcription factor binding element in the upstream regulatory sequence for Smyd3 has been linked to a heightened risk for oncogenesis." (PMID 17092350, 2006). "Similarly, we detected a reduction in levels of the methyltransferase SMYD3, which is implicated in hepatocellular carcinoma." (PMID 28137721, 2017). "Recent research indicates that SMYD3 overexpression can contribute to the EMT‐related gene overexpression in sorafenib‐resistant hepatocellular carcinoma cells." (PMID 39092293, 2024). "SMYD3 overexpression promotes the tumorigenicity and intrahepatic metastasis of hepatocellular carcinoma cells by upregulating CDK2 and MMP2 expression." (PMID 39482529, 2024). "This work identified a novel small molecule ZYZ384 targeting SMYD3 with antitumor activity and impaired hepatocellular carcinoma tumor growth by reducing H3K4 trimethylation of the Rac1 promoter triggering the tumor cell cycle arrest through the AKT pathway." (PMID 39286779, 2024). "Taken together, our study developed a novel molecule ZYZ384 targeting SMYD3 for hepatocellular carcinoma via reducing H3K4 trimethylation of the Rac1 promoter." (PMID 39286779, 2024). "In hepatocellular carcinoma, SMYD3 transcriptionally represses target gene expression by associating with the NuRD (MTA1/2) complex to regulate proliferation." (PMID 39482529, 2024). "Another in vitro study involving HepG2 hepatoma cells concluded that HBx-SMYD3 interaction, guided by the downstream target gene c-myc, promoted cell proliferation." (PMID 38489292, 2024). "ZYZ384 targeted SMYD3 with antitumor activity and impaired hepatocellular carcinoma tumor growth by reducing H3K4 trimethylation of the Rac1 promoter triggering the tumor cell cycle arrest through the AKT pathway." (PMID 39286779, 2024). "A recent report indicated that gene locus amplification resulted in SMYD3 upregulation in hepatocellular carcinoma." (PMID 37237385, 2023). "Knockdown of MTA1 or MTA2 had the same effect as knockdown of SMYD3 on proliferation and invasion of hepatocellular carcinoma cells." (PMID 36575438, 2022). "In vivo, SMYD3 overexpression promotes disease progression in pancreatic cancer (PC), lung cancer, hepatocellular carcinoma (HCC), colorectal cancer (CRC), gastric cancer (GC), breast cancer, esophageal squamous cell carcinoma, and ovarian cancer." (PMID 35495117, 2022). "SMYD3 is overexpressed in different types of tumors, including breast, gastric, pancreatic, colorectal, lung, and hepatocellular carcinoma." (PMID 34201935, 2021). "Knockdown of SMYD3 by RNAi has been reported to result in decreased cell proliferation in hepatocellular carcinoma, breast, cervical and esophageal cell lines and also in oncogenic KRAS -driven pancreatic cancer and lung adenocarcinoma cell lines." (PMID 29856759, 2018). "Subsequent experiments employing individual sgRNAs in three hepatocellular carcinoma cell lines reported to be dependent on SMYD3 activity showed little response to ablation of protein expression." (PMID 29856759, 2018). "SMYD3 (SET-and MYND-domain containing protein 3) is a H3-K4 MT and sequence-specific DNA binding protein that is over-expressed in other cancers, such as colorectal and hepatocellular carcinomas." (PMID 18980680, 2008).